GP6 (glycoprotein VI platelet)
Diseases named in the same sentence as GP6 in open-access papers (continued):
Sharing a sentence is not in itself a finding about the gene and the disease.
cardiac hypertrophy (2 papers, 2021). "Notably, leukocyte extravasation signaling, GP6 signaling, cardiac hypertrophy signaling, and PI3K signaling in B lymphocytes were predicted to be increasingly activated in the carboplatin-resistant TO, as demonstrated by pathways represented with shades of orange." (PMID 34440225, 2021). "Eight pathways were common between muscle and fat: acute phase signaling, senescence pathway, cardiac hypertrophy, IL-8 signaling, CXCR4 signaling, HMGB1 signaling, GP6 signaling and PDGF signaling." (PMID 33923976, 2021).
endometrial cancer (2 papers, 2022 to 2023). Primary or metastatic malignant neoplasm involving the endometrium (mucous membrane that lines the endometrial cavity). "It has previously been reported that the GP6 signaling pathway may play a crucial role in the metastasis of endometrial cancer and could be involved in the malignant behavior of parathyroid tumors." (PMID 36106120, 2022).
glioma (2 papers, 2021 to 2024). A benign or malignant brain and spinal cord tumor that arises from glial cells (astrocytes, oligodendrocytes, ependymal cells). "When comparing stages 1–2 and 3–4 ACCs, acute phase response signaling, LXR/RXR activation, production of nitric oxide and reactive oxygen species in macrophages, GP6 signaling pathway, and glioma invasiveness signaling were upregulated in stages 3–4 ACCs." (PMID 34359790, 2021).
Insulin resistance (2 papers, 2015 to 2023). Increased resistance towards insulin, that is, diminished effectiveness of insulin in reducing blood glucose levels. "Of the markers describing insulin resistance, HOMA2-IR index was found to be related to the same glycan structures as fasting insulin—GP21 and GP6 (padj = 6.572x10-03 and 2.08x10-02, respectively)." (PMID 37079606, 2023).
oral cancers (2 papers, 2014 to 2018). "A large multicentre study reported HPV DNA in 4% of 766 oral cancers using the consensus PCR primers GP5+/GP6+." (PMID 29580212, 2018). "Also, the prevalence of HPV was numerically, but not significantly, lower in studies of oral cancers that analysed HPV DNA types either using other types of primers or those that did not report the primers used than those using GP5+/GP6+ primers." (PMID 25515630, 2014).
Viral infections (2 papers, 2007 to 2016). "Viral infections have been detected by PCR using the MY09/MY11 oligoprimers alone or followed by nested PCR with GP5+/GP6+ primer pairs." (PMID 17201927, 2007).
bone marrow failure (1 paper, 2020). "This includes genes mutated in rare hematological syndromes (ADA, GP6, IL17RA, PRF1, and SEC23B), reported in prior MDS/AML or inherited bone marrow failure (IBMF) series (DNAH9, SH2B3, and NAPRT1), or novel loci where loss-of- function of the identified germline variants was demonstrated (DHX34)." (PMID 32098966, 2020).
breast tumors (1 paper, 2024). "Canonical Pathway Analysis of DEGs identified an enrichment in GP6, PKCθ, TLR, NF-ƙB signaling and dendritic cell maturation biological processes in NK cell-infiltrated breast tumors, which also showed negative scores for IL-6 signaling-related genes." (PMID 38167224, 2024).
cardiomyopathy (1 paper, 2023). A disease of the heart muscle or myocardium proper. "By contrast, other pathways clearly showed opposite trends, such as oxidative phosphorylation, necroptosis signaling, GP6 signaling in SDM, or fatty acid oxidation, ILK and RHOA signaling, and cardiomyopathy signaling pathway in LDM." (PMID 36835504, 2023).
cervical (1 paper, 2006). "The prevalence of cervical HPV was 66.1% (238 of 360): 114 samples were positive with the MY09/MY11 primer pair, 50 were positive with the GP5+/GP6+ primer pair, and 74 were positive by nested PCR." (PMID 16832413, 2006).
cervical tumors (1 paper, 2018). "Using the published GP5/GP6 PCR protocol we established our HPV positive cancer sample sets of 137 oropharyngeal and 121 cervical tumors." (PMID 30161236, 2018).
demyelination (1 paper, 2023). "Thus, upregulation of the GP6/collagen pathway in chronic de/remyelinating white matter suggests a previously unrecognized role for collagens in the context of chronic demyelination and may have relevance to progressive MS and remyelination failure." (PMID 37180951, 2023).
dilated cardiomyopathy (1 paper, 2023). Cardiomyopathy which is characterized by dilation and contractile dysfunction of the left and right ventricles. "These were the two SDM-associated pathways, necroptosis, GP6 signaling, and the four LDM-associated pathways, fatty acid β-oxidation, ILK, RHO, and dilated cardiomyopathy signaling that characterize metabolic SOL muscle changes in short vs. long duration mission conditions in spaceflight." (PMID 36835504, 2023). "Large scale proteomics (space omics) identified two canonical protein pathways associated to muscle weakness (necroptosis, GP6 signaling/COL6) in SDM and four key pathways (Fatty acid β-oxidation, integrin-linked kinase ILK, Rho A GTPase RHO, dilated cardiomyopathy signaling) explicitly in LDM." (PMID 36835504, 2023). "Fatty acid β-oxidation, ILK, RHOA, and dilated cardiomyopathy signaling characterize LDM exposure whereas two other pathways (necroptosis and GP6 signaling) characterize SDM exposure." (PMID 36835504, 2023).
Hereditary breast cancer (1 paper, 2020). Breast carcinoma that has developed in relatives of patients with history of breast carcinoma. "The top pathways included hereditary breast cancer, role of BRCA1 in DNA damage response, molecular mechanisms of cancer, and ATM and GP6 signalling pathways." (PMID 32724790, 2020).
invasive ductal carcinomas (1 paper, 2005). "In the present study, application of the GP5+/GP6+ assay using an arbitrary DNA quantity in the PCR indicated 5/26 (19%) invasive ductal carcinomas were HPV positive." (PMID 16288661, 2005).
pancreatic cancer (1 paper, 2021). "The top pathways suggested tRNA splicing, vitamin C transport, apelin liver signaling, metabolism of aryl hydrocarbon receptor (AHR) signaling, glycoprotein VI platelet (GP6) signaling, and SPINK1 pancreatic cancer pathway." (PMID 34685781, 2021).
pharyngeal cancer (1 paper, 2014). "Additionally, HPV prevalence was numerically, but not significantly, lower in pharyngeal cancer studies that assessed HPV DNA types using other type primers than in those that used either GP5+/GP6+ or MY09/MY11 primers." (PMID 25515630, 2014).
schizophrenia (1 paper, 2023). A major psychotic disorder characterized by abnormalities in the perception or expression of reality. "This comparison revealed that GP6 signaling, a pathway implicated in schizophrenia, and TREM1 signaling, which is related to inflammation and glial activation, are uniquely activated in aged motor neurons." (PMID 37154159, 2023).
tonsillar cancer (1 paper, 2014). "The prevalence of HPV was numerically, but not significantly, lower in studies of tongue and tonsillar cancer that had analysed HPV DNA types using only a primer that included GP5+/GP6+ than in studies using alternative primers." (PMID 25515630, 2014).
unstable angina (1 paper, 2020). "In this study, we examined the associations between polymorphisms in GP6 (rs1671152), PEAR1A (rs12566888), MRVI1 (rs7940646), PIK3CG (rs342286), JMJD1C (rs10761741), and SHH (rs2363910) and unstable angina." (PMID 33076381, 2020). "The results of this study suggest a lack of association between GP6 (rs1671152), PEAR1A (rs12566888), MRVI1 (rs7940646), PIK3CG (rs342286), JMJD1C (rs10761741), SHH (rs2363910), and unstable angina." (PMID 33076381, 2020).
tumor (44 papers, 2016 to 2025). "ROC analysis showed good differentiation of the two tumor groups by expression level of GP6 and THBS4." (PMID 40303998, 2025). "HC + SEQ detected HPV DNA in five samples (39%) the four that tested positive by PCR using the GP5+/GP6+ primers and one additional tumor (Tumor 13)." (PMID 38898085, 2024). "Nested PCR using MY09/MY11 and GP5+/GP6+ as well as PGMY09/11 L1 consensus primers were performed to investigate the presence of HPV DNA in the tumours." (PMID 29580212, 2018). "As a platelet-specific collagen receptor, GP6 is known to mediate platelet adhesion and activation, which may indirectly influence tumor progression through platelet-tumor microenvironment crosstalk." (PMID 40303998, 2025). "Interestingly, GP6 signaling not only regulates normal hemostasis but also contributes to cardiovascular disease, inflammation, coagulation control, and tumor metastasis." (PMID 32751271, 2020). "Our current study identified several collagen genes that were upregulated in metastatic EC, suggesting that the upregulated collagens may activate GP6 signaling and protect the EC cells from immunosurveillance and promote tumor metastasis." (PMID 32315343, 2020). "While in one unpublished study of ours, using GP5+ and GP6+ primers that amplify a broad spectrum of HPV genotypes, we found 17 out of 136 FFPE oropharynx tumor samples were HPV positive." (PMID 35708339, 2022). "The results of immunohistochemistry showed that MAK, GP6 and TEMEM156 were significantly highly expressed in tumor tissues, and DCTN2 was highly expressed in normal tissues." (PMID 34722557, 2021). "Nonetheless, the detection of abundant DNA of two relatively uncommon HPV types in a tumor that was positive by HC + SEQ but not by GP5+/GP6 + PCR illustrated the breadth of sensitivity of the contemporary HC + SEQ approach to detect HPV in tumors." (PMID 38898085, 2024). "Interestingly, transcriptome pathway enrichment analysis demonstrates that MGF inhibits tumor growth, metastasis and angiogenesis by multi-targeting of mitochondrial oxidoreductase and fatty acid β-oxidation metabolism, PPAR, SIRT, NFκB, Stat3, HIF, Wnt and GP6 signaling pathways." (PMID 34924998, 2021).
cancer (35 papers, 2013 to 2025). A tumor composed of atypical neoplastic, often pleomorphic cells that invade other tissues. "Accordingly, MGF treatment targets mitochondrial energy metabolism (fatty acid oxidation, sirtuin, TCA) NFκB, PPAR, Wnt and GP6 signaling to suppress cancer cell migration-metastasis processes." (PMID 34924998, 2021). "A total of 52 canonical pathways were activated or inhibited in cancer pathogenesis, including antigen presentation, mitochondrial dysfunction, GP6 signaling, EIF2 signaling, and glutathione-mediated detoxification." (PMID 31258820, 2019). "The GP6 signaling pathway was primarily thought to be involved in platelets and their precursor megakaryocyte activation, which might shield circulating cancer cells from immunosurveillance and promote metastasis." (PMID 36106120, 2022). "In addition, the GP6 pathway is known to be a requisite for formation of platelet aggregation, which in turn plays a role in cancer development, progression, and metastasis." (PMID 36077735, 2022). "In contrast, pathways predicted to be inhibited in R vs. NR patients included the “PD-1, PD-L1 cancer immunotherapy”, the “MSP-RON signaling in macrophages” and the “GP6 signaling” pathways." (PMID 37739939, 2023). "The detection of HPV types in cancer is commonly done by different PCR assays which utilize various universal primers including MY09/MY11, GP5/GP6, GP5+/GP6+, CP65/CP70, CP66/CP69, and SPF1/SPF2 designed during 1990s or earlier." (PMID 26766963, 2016). "Among the signalling pathways discovered included the DNA repair and Androgen and ATM signalling pathways for TNBC and the DNA damage response, molecular mechanisms of cancer, and ATM and GP6 signalling pathways for non-TNBC." (PMID 32724790, 2020).
infection (17 papers, 2012 to 2025). The state of being infected such as from the introduction of a foreign agent such as serum, vaccine, antigenic substance or organism. "With infection, in platelets, associations changed and expression of F2RL3 and GP6 both positively correlated with TLR6, TLR9, RIG-I, MDA5, LGP2, and CGAS." (PMID 40825056, 2025). "In downregulated groups, most of the function categories were enriched at the infection time points from 6 hpi to 24 hpi in GP6." (PMID 34876002, 2021). "At 5 dpi, infection efficiency of GP6 and L07 increased to 53.21 and 56.24% respectively while it was calculated as 5.39% in H99." (PMID 34876002, 2021). "The 56 gene products (Gps) of T7 are categorised as early (class I: Gp0.3-1.3), middle (class II: Gp1.6-6.3) and late (class III: Gp6.5-19.5) to reflect the timing of their expression during the infection process." (PMID 28486695, 2017). "During the course of the infection, two middle gene products, Gp3 and Gp6, which are exo- and endonucleases, respectively, degrade the host chromosome and thereby provide resources to drive phage gene expression and DNA replication." (PMID 28486695, 2017). "Infection efficiency of GP6 and L07 was 40.02 and 42.69% at 3 dpi, while it was 0.93% in H99." (PMID 34876002, 2021). "Infection with MDR pathogens, as seen in GP2 and GP6, induced oxidative stress and persistent inflammation, impairing tissue repair." (PMID 40672366, 2025). "In the present study, GP6 and L07 MDEC showed high infection efficiency upon Agrobacterium infection, but H99 was recalcitrant to Agrobacterium infection, because of the low infection efficiency." (PMID 34876002, 2021). "In the present study, the MY09/MY11 and GP5+/GP6+ primers followed by DNA sequencing and type specific PCR were used to confirm the HPV genotypes and to identify the mixed infection." (PMID 24252426, 2013).
cardiovascular diseases (11 papers, 2015 to 2025). "Impact of GPVI polymorphisms on cardiovascular risk: genetic studies have linked polymorphisms in the GP6 gene, which encodes GPVI, to altered platelet function and increased cardiovascular disease risk." (PMID 40699681, 2025).
connective tissue disorder (1 paper, 2023). A disease involving the connective tissue. "Bioinformatics analysis showed significant changes in GP6 signaling, in the MSP–RON signaling in macrophages pathway and in networks associated with cardiovascular system development and function, connective tissue disorders and dermatological conditions." (PMID 37726509, 2023).
head and neck tumours (1 paper, 2018). "In the current study, we have used three different standard primer sets (MY09/MY11, GP5+/GP6+ and PGMY09/11) and nested PCR to detect HPV DNA in head and neck tumours, which increases the sensitivity compared to a single PCR reaction." (PMID 29580212, 2018).
GP6 also shares sentences with these, for which no sentence is quoted: Thrombocytopenia (14 papers); myocardial infarction (12); coronary artery disease (6); melanoma (6); Cerebral ischemia (5); colon carcinoma (5); acute myocardial infarction (4); atrial fibrillation (4); cerebral infarct (4); immune thrombocytopenia (4); ischemia (4); Thromboembolism (4); Alzheimer disease (3); Arthritis (3); dyslipidemia (3); Glanzmann thrombasthenia (3); Hyperglycemia (3); Lewis lung carcinoma (3); metabolic disease (3); ovarian carcinoma (3); bacterial infection (2); basal cell carcinoma (2); colorectal cancer (2); heart failure (2); hemorrhagic stroke (2); Hypertension (2); infarct (2); intracerebral hemorrhage (2); Miscarriage (2); Platelet disorders (2).
A further 52 diseases each share a sentence with GP6 in 2 papers or fewer.